CGAS (cyclic GMP-AMP synthase)
Diseases named in the same sentence as CGAS in open-access papers (continued):
Sharing a sentence is not in itself a finding about the gene and the disease.
primary effusion lymphoma (1 paper, 2022). A large B-cell lymphoma located in the body cavities, characterized by pleural, peritoneal, and pericardial fluid lymphomatous effusions and that is always associated with human herpes virus-8 (HHV-8). "To determine if caspases also suppress the cGAS/STING pathway in a cell type that is physiologically relevant for KSHV infection and tumorigenesis, we examined the activity of caspases in BC3 cells, a KSHV-infected B cell line derived from a primary effusion lymphoma (PEL) patient." (PMID 36255240, 2022).
proliferative diabetic retinopathy (1 paper, 2024). Advanced retinopathy due to diabetes mellitus characterized by the formation of new vessels in the retina. "In this study, our analysis of a published retinal RNA-seq dataset revealed significant upregulation of cGAS and STING expression in patients with proliferative diabetic retinopathy (PDR)." (PMID 38918759, 2024). "We found a significant upregulation of CGAS and STING genes in the RNA-seq data derived from retinal tissues of the patients with proliferative diabetic retinopathy." (PMID 38918759, 2024).
prostate tumors (1 paper, 2024). "Additionally, the activation of cGAS/STING during tumorigenic transformation has also been associated with another fork-processing nuclease, Mus81, in the therapeutic of CINII-stage prostate tumors, suggesting a causal relationship between cGAS sensing and DNA repair." (PMID 38630271, 2024).
protozoal infections (1 paper, 2018). "The cyclic GMP-AMP synthase (cGAS)-STING pathway is central for innate immune sensing of various bacterial, viral and protozoal infections." (PMID 29298342, 2018).
pulmonary aspergillosis (1 paper, 2025). "Conversely, during pulmonary aspergillosis, cGAS–STING pathway activation appears protective, as its inhibition exacerbates pulmonary damage." (PMID 41249509, 2025). "However, research has so far primarily relied on gene downregulation or pharmacological inhibition to assess the role of the cGAS–STING pathway in the context of aspergillosis." (PMID 41249509, 2025).
pulmonary edema (1 paper, 2023). Accumulation of fluid in the lung tissues causing disturbance of the gas exchange that may lead to respiratory failure. "Having determined the effects of cGAS deletion in LPS-induced pulmonary inflammation, we then explored whether cGAS deletion had the same efficacy for LPS-induced vascular permeability, pulmonary edema, and mortality." (PMID 38114479, 2023).
pulpitis (1 paper, 2021). Inflammation of the dental pulp. "The high expression of cGAS and STING in caries and pulpitis tissues in patients, which was associated with inflammatory progression." (PMID 34016129, 2021). "Pulpitis model was built in vitro to evaluated the effect of the cGAS-STING pathway in odontoblast-like cell line (mDPC6T) under inflammation." (PMID 34016129, 2021). "We also found high expression levels of cGAS and STING mainly in the odontoblast layer in caries tooth samples and pulpitis tooth samples compared with healthy tooth samples." (PMID 34016129, 2021). "The western blotting results showed that the expression of cGAS and STING in pulpitis tissues was much higher than that in normal tissues and caries tissues." (PMID 34016129, 2021). "To investigate the clinical importance of cGAS and STING in caries and pulpitis patients, we compared cGAS and STING expression levels in caries, pulpitis and normal tooth samples by western blotting and immunohistochemistry." (PMID 34016129, 2021).
radiation pneumonitis (1 paper, 2023). Inflammation of the lung due to harmful effects of ionizing or non-ionizing radiation. "Moreover, translational investigations using patient samples collected before and after thoracic radiotherapy provided additional evidence supporting the association between cGAS-STING signaling activity, CCL2 upregulation, and the development of radiation pneumonitis." (PMID 37667317, 2023).
renal cell carcinoma (1 paper, 2023). "There was a significant association between the expression value of hub genes of the identified cluster including those related to cGAS-STING pathway and DNA damage response, and the prognosis of renal cell carcinoma." (PMID 37319163, 2023).
retinal ischemia (1 paper, 2023). A ischemic disease that involves the retina. "In this study, we investigated the effect of the inflammatory cascade on dsDNA recognition and examined the neuroprotective effect of the cyclic GMP-AMP (cGAMP) synthase (cGAS) antagonist A151 on a retinal ischemia/reperfusion (RIR) mouse model." (PMID 37726272, 2023).
Rhabdoviridae infection (1 paper, 2023). "Vesicular stomatitis virus (VSV) replication is increased in absence of cGAS in vivo; indeed, cGAS/STING signalling is activated following Rhabdoviridae infection through two different non-canonical mechanisms." (PMID 37077526, 2023).
schistosomiasis (1 paper, 2022). An infectious disease caused by parasitic trematodes of the genus Schistosoma that colonize human blood vessels and release eggs that can cause granulomatous reactions leading to acute (swimmer's itch or acute schistosomiasis syndrome) or chronic disease. "Our study revealed cGAS as a novel functional receptor for the recognition of invading Schistosoma, paving the way for the development of novel strategies to treat schistosomiasis." (PMID 35108342, 2022). "Therefore, during the natural infection of Schistosoma, cGAS-mediated sensing of parasite-derived DNA might be critical for the induction of the type I IFN response, at least in macrophages, which might ultimately contribute to the pathogenesis of schistosomiasis." (PMID 35108342, 2022).
serous ovarian cancer (1 paper, 2024). "Empirical evidence supports this conjecture and documents that cisplatin elicits pervasive cell senescence contingent on the cytosolic DNA sensor cyclic GMP-AMP synthase (CGAS) in high-grade serous ovarian cancer (HGSOC)." (PMID 38358910, 2024).
sickle cell disease (1 paper, 2023). Sickle cell anemias are chronic hemolytic diseases that may induce three types of acute accidents: severe anemia, severe bacterial infections, and ischemic vasoocclusive accidents (VOA) caused by sickle-shaped red blood cells obstructing small blood vessels and capillaries. "A Previous study has confirmed that cell-free mtDNA triggers NETs formation by the TLR9 pathway during lung transplantation and by the cGAS-STING pathway in sickle cell disease." (PMID 37794018, 2023).
silicosis (1 paper, 2023). Silicosis is a respiratory disease caused by breathing in (inhaling) silica dust. "The fifth disorder showing inflammation development associated with the cGAS–STING pathway is silicosis." (PMID 37686127, 2023).
skin infection (1 paper, 2025). An inflammatory process affecting the skin, caused by bacteria, viruses, parasites, or fungi. "In skin infection models, the cGAS-STING antagonizes the TLR signaling pathway, suppressing the production of the key inflammatory cytokine IL-1β and neutrophil recruitment." (PMID 40697819, 2025).
Spinal instability (1 paper, 2024). "On the one hand, the cGAS-/- mice model of spinal instability indicates that the loss of dsDNA receptors has a protective effect on IDD." (PMID 38725841, 2024).
synucleinopathies (1 paper, 2024). "Understanding the molecular mechanisms of α-syn–induced cGAS–STING–associated “mito-inflammation” in PD and related synucleinopathies may contribute to the identification of new targets for the treatment of these disorders." (PMID 39011416, 2024). "However, the precise molecular mechanisms underlying cGAS–STING pathway activation in PD and other synucleinopathies are not fully understood." (PMID 39011416, 2024).
T-cell lymphoma (1 paper, 2022). "In contrast, the application of BLK inhibitors in treating T-cell lymphoma (where BLK was shown as an oncogene) should be used with caution because inhibiting BLK may attenuate cGAS cytosolic retention leading to deficiency in cGAS activation and dampened T-cell recruitment into tumors." (PMID 35795661, 2022).
tendinopathy (1 paper, 2025). "In summary, macrophage PTP1B was shown to regulate mitochondrial dynamics via the JAK2/STAT3-OPA1 axis and trigger inflammation through activation of the cGAS/STING pathway, representing a key mechanism underlying the progression of tendinopathy." (PMID 41132674, 2025).
Urea (1 paper, 2025). "Notably, IFNAR1, TBK1, and TRAF6-downstream components of cGAS-STING signaling -were significantly upregulated in the Urea + OGD group, suggesting engagement of DNA damage-driven inflammatory mechanisms." (PMID 41286951, 2025).
uremia (1 paper, 2023). A clinical syndrome associated with the retention of renal waste products or uremic toxins in the blood. "To study the effect of cGAS in uremia-induced systemic inflammation, we performed bilateral nephrectomy (BNx) in wild-type and cGAS knock-out mice and found that the gut leakage and blood uremia from both groups were similar." (PMID 37189826, 2023). "At 48 h after BNx, cGAS−/− and WT mice developed similar severity in uremia, as indicated by an increase in blood urea nitrogen and creatinine (respectively), but had significantly lower alanine transaminase levels, indicating less liver damage." (PMID 37189826, 2023).
uveal melanoma (1 paper, 2023). A melanoma derived from melanocytes of the uveal tract. "Collectively, these findings indicate that NPPDT‐56MESS functions as a chemotherapeutic agent and cGAS‐STING pathway agonist, representing a combination chemotherapy and immunotherapy strategy that provides novel modalities for the treatment of uveal melanoma." (PMID 37807827, 2023).
uveitis (1 paper, 2026). An inflammatory process affecting a part of or the entire uvea. "In this study, we demonstrated evidence for the activation of the cGAS‒STING pathway in a mouse model of LPS-induced uveitis." (PMID 41487469, 2026). "Our research focused on the impact of the cyclic guanosine monophosphate-adenosine monophosphate synthase (cGAS)–stimulator of interferon genes (STING) pathway on retinal inflammation and employed an endotoxin-induced uveitis (EIU) model." (PMID 41487469, 2026). "Our current in vivo research using animal models confirmed that the cGAS‒STING pathway is involved in retinal inflammatory damage, suggesting that targeting this pathway could be a promising approach for treating uveitis." (PMID 41487469, 2026).
varicocele (1 paper, 2025). A condition characterized by the dilated tortuous veins of the spermatic cord with a marked left-sided predominance. "Chlorogenic acid inhibits cGAS/STING-mediated NLRP3 activation in varicocele, restoring mitochondrial homeostasis." (PMID 40331931, 2025). "Autophagy inhibits pyroptosis hyperactivation by degrading the NLRP3 inflammasome, e.g., chlorogenic acid inhibits NLRP3 through the cGAS/STING pathway and ameliorates varicocele." (PMID 40331931, 2025).
viral myocarditis (1 paper, 2024). Myocarditis that is caused by an infection with a viral agent. "Recent research has shown that the cGAS-STING pathway has a dual role in viral myocarditis." (PMID 38803502, 2024). "In addition to its role in viral myocarditis, the cGAS-STING pathway is also significant in non-infectious myocarditis and microbial infections." (PMID 38803502, 2024).
vulvar cancer (1 paper, 2024). "Activation of the cGAS-STING pathway in human cardiac fibroblasts remains unclear; however, evidence from studies on mouse embryonic fibroblasts and patient-derived vulvar cancer-associated fibroblasts suggests its presence." (PMID 39591455, 2024).
Wilms tumor (1 paper, 2023). An embryonal neoplasm characterized by the presence of epithelial, mesenchymal, and blastema components.
Wiskott-Aldrich syndrome (1 paper, 2021). Wiskott-Aldrich syndrome (WAS) is a primary immunodeficiency disease characterized by microthrombocytopenia, eczema, infections and an increased risk for autoimmune manifestations and malignancies. "Here we will focus on the prototype cytoskeletal-related immune disease, Wiskott-Aldrich syndrome (WAS), the first example of a cytoskeletal-related primary immune deficiency with deregulated type-I interferon driven by cGAS-STING activation." (PMID 34084165, 2021).
tumor (1,303 papers, 2016 to 2026). "In conclusion, our results demonstrate that the cGAS-STING pathway play a vital role in tumor immunity, with high expression associated with increased immune cell infiltration and improved patient survival." (PMID 40830678, 2026). "G3BP1 activates the NF-κB signaling pathway at the level of phosphorylation through cyclic GMP-AMP synthase (cGAS), thereby facilitating senescence-associated tumor growth." (PMID 41513625, 2026). "In striking contrast to their tumor suppressive roles, cGAS and STING have also been implicated in promoting tumor burden and worse disease outcomes in models of cancer." (PMID 40008133, 2025). "They promote immunogenic cell death (ICD), releasing damage-associated molecular patterns and tumor antigens that activate innate immune sensors like the cGAS-STING pathway." (PMID 41516303, 2025). "Conversely, CGAS was negatively correlated with M2 macrophages, a cell type typically associated with tumor promotion." (PMID 40786100, 2025). "Before examining potential roles of VRAC in the cGAMP-mediated anti-tumor immune response, we used a cGAS-deficient MC38 cell line to validate that tumor-produced cGAMP affects cancer growth in vivo." (PMID 41419196, 2025). "The elevated secretion of IFN-β is likely linked to the MnO2-mediated cGAS-STING signaling pathway on the surface of the tumor vaccine." (PMID 40291558, 2025). "The inactivation of the cGAS-STING pathway or mutations in STING can facilitate tumor immune evasion and contribute to therapeutic resistance." (PMID 40052963, 2025). "Pathogenic infection, endogenous DNA damage, and DNA from tumor cells are the three major stimuli of the cGAS-STING signaling cascade." (PMID 40552157, 2025). "Activation of the cGAS–STING pathway has been linked to increased tumor immunogenicity and enhanced dendritic cell activity with varying influence depending on tumor type, stage, and immune microenvironment." (PMID 40417178, 2025). "K432T and G303E, the two tumor-related mutations, located at DNA-binding sites of cGAS, lead to a diminished capability to form cGAS condensates and a decrease in cGAMP." (PMID 40104511, 2025). "EFTUD2 is a potential diagnostic and prognostic marker for LUAD, associated with immune infiltration, the tumor microenvironment, the cGAS-STING pathway, m6A modification, and glycolysis." (PMID 40236649, 2025). "Recently, it has been suggested that in PDAC tumors, mitochondrial DNA in tumor cells induces the activation of the cGAS-STING signaling in tumor-associated macrophages, which promotes cellular secretion of INFα." (PMID 40432130, 2025). "This review explores the mechanisms underlying both the anti-tumor and protumor roles of the cGAS-STING pathway, with a focus on potential therapeutic approaches, and the challenges faced in their clinical application, along with corresponding solutions." (PMID 40052963, 2025). "We first assessed the association between stromal VCAN expression and tumor cell-intrinsic cGAS–STING expression in CRC." (PMID 40451897, 2025). "We identified PRMT1 in GC cells as a prognostic factor that not only drives tumor-associated macrophages (TAMs) toward tumor-promoting subtypes but also reduces apoptosis in GC cells by suppressing the cGAS-STING pathway." (PMID 40858547, 2025). "These responses are also triggered by the immunogenic cell death of tumor cells, which release damage-associated molecular patterns activating the DNA-damage-related proinflammatory cGAS-STING-IFN1 signaling pathway." (PMID 40473848, 2025). "Here, we revealed a novel association between PRMT1 inhibition of tumor macrophage polarization and cGAS/STING in a GC model." (PMID 40858547, 2025). "In this study, we observed that both CH25H and its downstream metabolite 25HC were upregulated in tumor‐associated MDSCs, which in turn suppressed the cGAS–STING pathway." (PMID 41020041, 2025).